KCNMA1 (potassium calcium-activated channel subfamily M alpha 1)
Diseases named in the same sentence as KCNMA1 in open-access papers (continued):
Sharing a sentence is not in itself a finding about the gene and the disease.
breast carcinoma (continued). "In the present study, our results from global exon array analysis showed higher expression of KCNMA1 in metastatic breast cancers located in brain than in metastatic breast cancers in other organs." (PMID 19640305, 2009). "We performed Global exon array to study the expression of KCNMA1 in metastatic breast cancer to brain, compared its expression in primary breast cancer and breast cancers metastatic to other organs, and validated the findings by RT-PCR." (PMID 19640305, 2009). "Expression of the KCNMA1 gene was higher in breast tumor specimens from brain metastases compared to specimens from primary breast cancer or metastases to other organs." (PMID 19640305, 2009). "Previous studies reported that KCNMA1 may be involved in various human tumorigenesis processes, such as prostate cancer, breast cancer, cervical cancer, and colorectal cancer." (PMID 37601683, 2023). "It needs to be emphasized that mutations in KCNMA1 gene are rare – only 15 (7 in luminal A, 5 in luminal B, 2 in HER2, 1 in basal subtype) in breast cancer, although the gene is overexpressed and the cause of overexpression is unknown." (PMID 32586284, 2020). "However, increased expression of KCNMA1 was found in metastatic breast cancer in the brain compared to metastatic breast cancers in other organs, which suggests a more complicated pathological role for the BK channel in tumor metastasis." (PMID 24053408, 2013). "The KCNMA1-amplified breast cancer (MFM223) and prostate cancer (PC3; positive control) cell lines were strongly positive for BK channels, while non-amplified breast cancer cell lines T47D and MCF7 were only weakly positive or negative as evaluated by immunofluorescence." (PMID 22899999, 2012). "However, immunofluorescence revealed moderate to strong KCNMA1 expression in eight out of nine frozen breast cancer specimens irrespectively of KCNMA1 gene copy number." (PMID 22899999, 2012). "In breast cancer, KCNMA1 is amplified in a rare subgroup of breast cancers with poor prognosis." (PMID 22899999, 2012). "Furthermore, treating cells with siRNA that targeted the KCNMA1 gene inhibited the invasion of breast cancer cell lines to a similar extent as did treating them with IBTX." (PMID 19640305, 2009). "Moreover, knocking down KCNMA1 reduced proliferation by 58% in T47D breast cancer." (PMID 34885254, 2021). "Notably, one report showed a role for KCNMA1 in breast cancer invasion and metastasis to brain." (PMID 22899999, 2012). "Our results clearly show that metastatic breast cancer cells exhibit increased BKCa channel activity, leading to greater invasiveness and transendothelial migration, both of which could be attenuated by blocking KCNMA1." (PMID 19640305, 2009). "Therefore, determining the relative abundance of KCNMA1 in breast cancer metastases to brain and understanding its role in brain metastasis may allow us to target KCNMA1 for its prognostic and possibly therapeutic potential." (PMID 19640305, 2009). "Breast cancer studies included E1 (KCNMB1), E4 (KCNN3), E9 (KCNH1, KCNK15), E15 (KCNT2), E22 (KCNK5, KCNK15), E33 (KCNQ1-OT1), E38 (KCNMA1), E48 (KCNJ9), and E63 (KCNK12)." (PMID 40867621, 2025). "In contrary, the maximum of KCNMA1 was detected in the later G1 stage and decreased to S phase of the cycle in MCF-7 breast cancer cells." (PMID 30872711, 2019). "On the other hand, in the metastatic breast cancer cell lines MCF7, MDA-MB-231, and MDA-MB-361, KCNMA1 promotes cell invasiveness and transendothelial migration, which could be attenuated by siRNA knockdown or inhibition with Iberiotoxin." (PMID 30791468, 2019). "Almost all (8 of 9; 89%) KCNMA1 amplified, but only 11 of 25 (44%) non-amplified breast cancers were AR-negative." (PMID 22899999, 2012).
breast carcinoma (continued). "To explore the association between amplification of KCNMA1 and tumour cell proliferation, we constructed a TMA with 34 specimens enriched for KCNMA1 amplified breast cancers (9 with and 25 without KCNMA1 amplification) using two tissue cores per specimen." (PMID 22899999, 2012). "Furthermore, advances in the identification of contributing factors including the role of KCNMA1 in the metastatic processes, as well as understanding its function and regulation may result in the development of targeted agents to suppress BKCa channel over expression in breast cancers." (PMID 19640305, 2009). "KCNMA1-mRNA expression was by far highest in MFM223 among all 26 analyzed cancer cell lines using quantitative real-time PCR, and more than 100-fold higher than in the non-amplified breast cancer cell line MCF7." (PMID 22899999, 2012).
glioma (31 papers, 2009 to 2024). A benign or malignant brain and spinal cord tumor that arises from glial cells (astrocytes, oligodendrocytes, ependymal cells). "On the contrary, AQP4-OAPs caused a statistically significant upregulation of the KCNMA1 in U87 glioma cells in line with the elevated outward currents recorded in these cells." (PMID 39200356, 2024). "Similar mutual regulations of p-BRAF and KCNMA1 levels were then recapitulated in human glioma cells with the BRAF mutation." (PMID 36763212, 2023). "Ca2+-activated K+ channel BK (big conductance) channel (Kca1.1 encoded by KCNMA1) expression level was positively correlated with the degree of glioma malignancy." (PMID 36768856, 2023). "This co-dependency was recapitulated in human cells where elevated KCNMA1 was observed in gliomas with BRAFGOF mutation." (PMID 36763212, 2023). "Therefore, the co-dependency of KCNMA1 and p-BRAF is highlighted as critical for BRAF-mutated glioma progression and, due to this, KCNMA1 could be a valuable potential therapeutic drug target for the treatment of tumors with BRAF mutations." (PMID 36763212, 2023). "In particular the expression of KCNMA1, which encodes a component of a K+ exporting channel whose function is modulated by Ca++, has been linked to tumor cell proliferation in prostate cancer, cell migration in glioma and antineoplastic drug resistance in melanoma cells." (PMID 21072171, 2010). "These two shRNAs showed impeded KCNMA1 expression and significantly reduced glioma cell proliferation in the DBTRG-05MG cell line as compared with the controls." (PMID 36763212, 2023). "We propose that, in depolarized glioma cells with BRAF mutations, high KCNMA1 levels act to repolarize membrane potential and facilitate cell growth." (PMID 36763212, 2023). "The sample P1, which was diagnosed as a hair cell astrocytoma and classified as a WHO grade I glioma, exhibited high levels of KCNMA1 expression while signals from the other four samples were either low or undetected." (PMID 36763212, 2023). "This p-BRAF and KCNMA1 level codependency in mammalian cells was highly reminiscent of that previously observed in Drosophila RafGOF glioma brains." (PMID 36763212, 2023). "Taken together, our data indicates that KCNMA1 expression is upregulated in human BRAFV600E glioma cells." (PMID 36763212, 2023). "For example, mRNA and protein analyses showed that Kca channel subunit alpha-1 (KCNMA1) was amplified in 90% of high-grade gliomas samples from patients, as well as in the human high-grade glioma cell line U-87." (PMID 33198244, 2020). "To double-check the expression pattern of KCNMA1, univariate Cox proportional hazards regression was conducted to estimate the relationship between glioma survival and KCNMA1 expression level in the three validation cohorts." (PMID 26235283, 2015). "Based on our investigation, we have concluded that KCNMA1 expression is not simply biased toward high grade gliomas, but is linked more specifically to the BRAF mutations that enhance tumor proliferation." (PMID 36763212, 2023). "KCNMA1 has been noted as highly expressed in glioblastomas (high grade gliomas)." (PMID 36763212, 2023). "Interestingly, we observed that the survival time of glioma was inversely and significantly correlated (hazard ratio <1) with KCNMA1 expression level in all three validation datasets, which is consistent with the finding from the UHC cohort." (PMID 26235283, 2015). "However, the weight of KCNMA1 is negative in this study, which means the gene expression of KCNMA1 is negatively correlated with glioma grade in the UHC cohort." (PMID 26235283, 2015). "Conducting an extensive search using PubMed on glioma/brain-cancer-related articles of ABCC8, ABCC9, KCNJ11, KCNJ8, AQP4, and KCNMA1 genes has yielded interesting results." (PMID 39200356, 2024). "In glioma cells, high levels of p-BRAFV600E leads to membrane depolarization and elevated KCNMA1 expression." (PMID 36763212, 2023).
glioma (continued). "In the glioma cell line, p-BRAF activated downstream signaling pathways accompanied by higher KCNMA1 expression." (PMID 36763212, 2023). "The co-dependency and mutual regulation of KCNMA1 and p-BRAF levels seems to be therefore confirmed for BRAFV600E glioma cells in a human context." (PMID 36763212, 2023). "Thus we propose that an unknown mechanism exists to relay the signals from p-BRAF to establish the KCNMA1 levels in glioma cells, and that this occurs without the involvement of p-MEK." (PMID 36763212, 2023). "In the present work, we showed that the AQP4 aggregation into the pathogenic AQP4-tetramer and AQP4-OAPs differently affected the expression profile of KCNMA1, KCNJ11, ABCC8, and ABCC9 genes but not of the KCNJ8 gene in the U87 glioma cell, evaluated by the RTPCR gene expression." (PMID 39200356, 2024).
Ataxia (25 papers, 2009 to 2025). Ataxia refers to impaired coordination of voluntary muscle movement. "Kcnma1 encodes the alpha subunit of the large conductance calcium-activated potassium BK channel in PCs, and loss-of-function mutations cause ataxia in mice." (PMID 38673939, 2024). "It is noteworthy that Itpr1, Calb1, Mtss1, and Kcnma1 are known to cause ataxia when mutated in human or mouse models." (PMID 38673939, 2024). "Mutations in KCNMA1 cause Liang–Wang syndrome, comprised of developmental delay, cerebellar ataxia, and variable neurological features including seizures and dystonia, with visceral malformations and death in infancy in the most severe cases." (PMID 35757096, 2022). "Collectively, these results suggest that downregulation of Kcnma1 and ensuing abnormalities in PN spiking patterns may underly PN dysfunction and ataxia." (PMID 39147737, 2024). "The BK channel gene KCNMA1 is highly expressed in PNs, and KCNMA1 mutation or deficiency disrupts the normal firing patterns of PNs and rhythm in DCN, ultimately causing cerebellar ataxia." (PMID 39147737, 2024). "Mice with Purkinje neuron-specific ablation of BK (PN-BK−/−) channels display ataxia, the ataxic symptoms of which resemble global Kcnma1 knockout mice." (PMID 37374132, 2023). "Downregulation of Kcnma1 transcripts or BK channel dysfunction has been reported in multiple models of cerebellar ataxia." (PMID 37374132, 2023). "At present, there are no patients with homozygous KCNMA1 alleles validated as functionally null for channel activity, but the ataxia, tremor, decreased strength, and hyperactivity in Kcnma1‒/‒ mice are symptoms observed at lower incidence among patients." (PMID 35819138, 2022). "In separate mouse models, complete knockout of Kcnma1 produces profound ataxia and Purkinje neuron firing impairment in mice, yet cerebellar degeneration is not observed." (PMID 35757096, 2022). "It will also be interesting to utilize Drosophila models to study other KCNMA1/hSlo1 mutations linked to PNKD3,6, 7 as well as LOF mutations in KCNMA1 linked to ataxia." (PMID 33449381, 2021). "Mice with an invalidation of the Kcnma1 gene are characterized by cerebellar ataxia in the form of an abnormal conditioned eye-blink reflex, abnormal locomotion and a pronounced deficiency in motor coordination." (PMID 28248227, 2016). "Other episodic and non-episodic movement disorders observed among KCNMA1 patients include dystonia, hypotonia, myoclonus, ataxia, and tremor." (PMID 34224328, 2021). "Interestingly, among the 24 PC genes with restored expression, seven genes (Abr, Calb1, Htr1b, Itpr1, Kcnip1, Kcnma1, and Mtss1) were part of a group of 80 PC-type-specific downregulated genes common to the SCA1, SCA2, and SCA7 mouse models and composed an ataxia molecular signature." (PMID 38673939, 2024).
Hypertension (24 papers, 2010 to 2024). The presence of chronic increased pressure in the systemic arterial system. "In a candidate gene study, a KCNMA1 intron 17 SNP (rs16934182, GRCh37 chr10: 78778734) was nominally associated with severe systolic hypertension (p = 0.03), and severe general hypertension (p = 0.04)." (PMID 32080354, 2020). "KCNMA1 is one among several genes considered to be involved in control of vascular tone and hypertension." (PMID 32080354, 2020). "Of those, 28 genes had more than 5 var-HpaII sites, and several of those have been reported the association with PE (PTPRN2, KCNMA1, and NFATC1), hypertension (SDK1), and placental development (SALL3)." (PMID 27293492, 2016).
glioblastoma (22 papers, 2009 to 2025). The most malignant astrocytic tumor (WHO grade IV). "In conclusion, our studies showed that the mitoBKCa channel in glioblastoma U-87 MG cells is composed of pore-forming subunits encoded by the KCNMA1 gene." (PMID 37401985, 2023). "Therefore, we aimed to verify the hypothesis that the KCNMA1 gene definitively encodes the protein responsible for the activity of the mitoBKCa channel in glioblastoma." (PMID 37401985, 2023). "The glioblastoma cell line DBTRG-05MG with the BRAFV600E mutation showed high levels of both p-BRAF and KCNMA1 with a correspondingly hyper-activated BRAF/MAPK pathway." (PMID 36763212, 2023). "Inconsistent conclusions have been drawn linking the KCNMA1 levels with glioblastoma malignancy." (PMID 36763212, 2023). "In our project, we used CRISPR/Cas9 technology in human glioblastoma U-87 MG cells to generate knockout cell lines lacking the α-subunit of the BKCa channel encoded by the KCNMA1 gene, which also encodes cardiac mitoBKCa." (PMID 37401985, 2023). "In particular, radiation-stimulated activation of Ca2+-dependent high conductance BK (KCa1.1, KCNMA1) and intermediate conductance IK (KCa3.1, SK4, KCNN4) K+ channels occurs in glioblastoma cells." (PMID 32390841, 2020). "In vitro studies proved that knockdown of KCNMA1 inhibited cell proliferation or invasiveness in different types of cancer, such as glioblastoma, breast and prostate cancer, although this not seemed to apply to all." (PMID 25397596, 2014).
diabetes (18 papers, 2015 to 2025). "Research has indicated that Kcnma1 plays a crucial role in maintaining mitochondrial homeostasis, with the loss of this gene being a key contributor to skeletal muscle loss in diabetes." (PMID 40650956, 2025). "Another transcriptome study on human PBMC described that KCNMA1 is upregulated in PBMC from patients with type 1 diabetes mellitus compared with a healthy control group." (PMID 36295826, 2022). "Although the expression and activity of Kcnma1 in the bladder is known to be decreased with diabetes, our data are the first to suggest this decrease is not reversed by glycemic control." (PMID 33200530, 2020).
channelopathy (17 papers, 2020 to 2025). Channelopathies are a group of diseases caused by the dysfunction of ion channel subunits or their interacting proteins. "Identifying and characterizing patient-associated variants is critical for understanding the monogenic basis of KCNMA1-linked channelopathy." (PMID 40785052, 2025). "Abnormal expression and mutations in the Kcnma1 gene are associated with several pathological conditions and are termed Kcnma1‐linked channelopathies." (PMID 38561252, 2024). "Human KCNMA1-linked channelopathy mutations are primarily associated with neurological conditions, including movement disorders, seizures, and intellectual disability." (PMID 36677942, 2023). "In this study, we evaluate the circadian rhythm of three recently generated mice models of human KCNMA1 channelopathy variants, Kcnma1N999S/WT, Kcnma1D434G/D434G, and Kcnma1H444Q/H444Q." (PMID 37728576, 2023). "Studies have reported that mutations in the KCNMA1 gene encoding the BKCa channel, known as KCNMA1-linked channelopathy in humans, are associated with neurological conditions such as movement disorders, seizures and developmental delay." (PMID 37841931, 2023). "Precision medicine for KCNMA1 and other channelopathies begins with classifying patient mutations into functional classifications." (PMID 36503451, 2023). "The term "KCNMA1-linked channelopathy" refers to a variety of clinically characterized degenerative symptoms caused by 16 uncommon KCNMA1 mutations that were discovered in 37 patients starting in 2005." (PMID 37727158, 2023). "The findings support the conclusion that KCNMA1-linked channelopathy, although symptomatically heterogenous and comprised predominantly of de novo variants, has the potential to be categorized as a monogenic disorder." (PMID 35819138, 2022). "Yet it has been challenging to distill KCNMA1-linked channelopathy into a cohesive GOF versus LOF symptomology because the existing patient data lack genetic pedigrees and diagnostic cross-comparability." (PMID 35819138, 2022). "Our findings further establish the stress-induced PNKD assay to delineate distinct symptomatic manifestations between GOF and LOF alleles, supporting its utility in a battery of neurobehavioral evaluations to define KCNMA1-linked channelopathy models." (PMID 35819138, 2022). "KCNMA1-linked channelopathy encompasses an array of neurological symptoms associated with clinical detection of a KCNMA1 variant." (PMID 35819138, 2022). "We have characterized the channel properties, neuronal activity, neurobehavioral phenotypes, and relative severity of three KCNMA1-linked channelopathy variants under equivalent conditions." (PMID 35819138, 2022). "Our observation of the successful use of stimulants in KCNMA1‐linked channelopathy corroborates the previously reported case treated with dextroamphetamine." (PMID 35141357, 2022). "KCNMA1‐linked channelopathy is also associated with mild to severe developmental delay and intellectual disability." (PMID 35141357, 2022). "PNKD is often the earliest presenting symptom of KCNMA1‐linked channelopathy and typically starts before the age of 24 months." (PMID 35141357, 2022). "Paroxysmal non‐kinesigenic dyskinesia (PNKD) in KCNMA1‐linked channelopathy is the most common symptom in patients harboring the KCNMA1‐N999S mutation." (PMID 35141357, 2022). "So far, only 70 patients around the world have been diagnosed with a newly identified rare syndrome known as KCNMA1-linked channelopathy." (PMID 35819138, 2022). "We found that movement disorders are a consistent symptom of KCNMA1-linked channelopathy across mutation types, present in 51/69 total patients." (PMID 34224328, 2021). "It is also important to note that KCNMA1-linked channelopathy is at an early stage of definition with respect to causation." (PMID 34224328, 2021).